RNU6-639P (RNA, U6 small nuclear 639, pseudogene)
Gene: Small nuclear RNA gene on chromosome 20 (43,796,437 to 43,796,543, reverse strand). Ensembl gene ENSG00000206801.
Homologues: Orthologues: chimpanzee U6 (97% identical), macaque U6 (92% identical), dog U6 (79% identical). Paralogues in human: RNU6-1145P (94% identical), RNU6-38P (94% identical), RNU6-1316P (92% identical), RNU6-20P (92% identical), RNU6-393P (92% identical), RNU6-434P (92% identical), RNU6-10P (91% identical), RNU6-16P (91% identical), RNU6-25P (91% identical), RNU6-29P (91% identical), RNU6-41P (91% identical), RNU6-46P (91% identical), and 1290 more.